IL6 (interleukin 6)
Diseases named in the same sentence as IL6 in open-access papers (continued):
Sharing a sentence is not in itself a finding about the gene and the disease.
immune dysfunction (continued). "IL-6 and G-CSF levels were not measured at 4 h, since it would be difficult to determine whether any significant differences were related to immune dysfunction or bacterial burden." (PMID 28796194, 2017). "Some proinflammatory cytokines, such as interleukin-1β (IL-1β), interleukin-6 (IL-6), interleukin-8 (IL-8), and tumor necrosis factor α (TNF-α), which usually are termed as ‘bad guys’, are reported to correlate with inflammation response and immune regulation as well as several immune diseases." (PMID 24718556, 2014). "The reason for this situation may be the presence of immune dysfunction in MDD patients, and low levels of IFN-α have the immunomodulatory function of activating monocytes and/or macrophages to enhance the production of various cytokines (e.g., TNF-α, IL-1, IL-6, etc.)by both." (PMID 39911552, 2024).
kidney disease (200 papers, 2008 to 2026). "At the same time, IL-6 has been implicated in the pathophysiology of cardiovascular and renal disorders as a major pro-inflammatory cytokine." (PMID 41677590, 2026). "The urinary IL-6 expression was greater in patients with IgAN, negatively correlated with eGFR, and positively correlated with uPCR, indicating the association of IL-6 with kidney disease progression." (PMID 38649936, 2024). "Interleukin-6 (IL-6) is a key inflammatory factor in kidney disease and is also recognized as a diagnostic marker and therapeutic target." (PMID 38179188, 2023). "Urinary IL-6 levels were associated with renal disease activity assessed by the renal SLE disease activity index." (PMID 37189804, 2023). "Although elevated levels of TIMP-1 and IL-6 have been associated with the development of kidney disease, data in this study indicate that kidney function is not affected despite a significant increase in these markers." (PMID 35204763, 2022). "The mediation analysis was performed testing several variables known to be linked to kidney disease, including C-reactive protein, IL-6, uric acid, azotemia, triglycerides, ApoA1, ApoB, and HbA1c, and that resulted associated with mitokines, (data not shown)." (PMID 33131010, 2021). "Interleukin, the multifunctional inflammatory cytokines are closely associated with various renal diseases and the injury of kidney residential cells, such as IL-6, CXCL8, IL-1β, IL-2 and IL-4." (PMID 32765640, 2020). "Further evidence for a link between IL-6 and kidney disorder is the inverse association of the eGFR with the circulating levels of proinflammatory markers, including IL-6." (PMID 29805315, 2018). "GG homozygotes in 174 G/C of IL6 polymorphism are characterized by higher values of estimated glomerular filtration rate based on the study Modification of Diet in Renal Disease (eGFR MDRD) (ml/min/1.73 m2)] and systolic mitral annular velocity (S)." (PMID 28827564, 2017). "In kidney diseases, the IL-6 levels are effective in predicting mortality risk." (PMID 40907786, 2025). "The interleukin-6 (IL-6) signaling pathway affects renal-resident cells, including podocytes, mesangial cells, endothelial cells, and tubular epithelial cells, and has been implicated in several renal diseases, including DN." (PMID 41369384, 2025). "Furthermore, enhanced circulating or urinary IL-6 levels have been associated with the risk of kidney disease progression in T1D and T2D patients." (PMID 39723211, 2024). "In addition, IL-6 inhibitors are expected to reduce risk of inflammation-associated cardio-vascular complications of kidney diseases." (PMID 39723211, 2024). "Logistic regression analysis revealed that younger age and moderate symptoms were risk factors for RP in children, while the presence of comorbidities (such as chronic heart, lung, liver, and kidney diseases), elevated IL-6 levels, and NLR were risk factors for RP in adults." (PMID 37702601, 2024). "In fact, TNFα and IL-6 levels were demonstrated to be strongly linked to renal disease progression." (PMID 36986825, 2023). "The increase in IL6 levels has been implicated in liver and kidney diseases." (PMID 36235007, 2022). "Indeed, the level of IL-6 is not only a marker of blood-membrane contact but also its level is influenced by underlying renal disease, co-morbid conditions, age and therapy applied." (PMID 32471186, 2020). "Ideally, we could have included other variants known to be related to the progression and severity of renal disease, such as those within inflammatory cytokine IL-6 and polymorphisms identified in a recent genome-wide association study as significantly associated with urine albumin excretion." (PMID 21054877, 2010). "Due to its importance for kidney diseases, one aim of the present study is to identify IL-6 as a possible mediator of the cellular crosstalk in an acidic milieu." (PMID 40217316, 2025).
kidney disease (continued). "Patients with kidney diseases often exhibit a microinflammatory state, characterized by elevated levels of interleukin-6 (IL-6), tumor necrosis factor-alpha (TNF-α), and C-reactive protein (CRP)." (PMID 41356816, 2025). "On the other hand, extensive research on the inflammatory response in renal disorders has shown that increased pro-inflammatory cytokines such as IL-6 and TNF-α can promote apoptosis." (PMID 39906624, 2025). "The cytokine IL-6 is a significant driver of inflammatory processes and additional it is stated that IL-6 signaling supports the progression of chonic kidney diseases." (PMID 40217316, 2025). "Studies have shown that reducing the level of IL-6 inflammatory factors can reduce the inflammatory response and improve the production of kidney disease." (PMID 40331191, 2025). "Increasing evidence highlights the critical role of IL-6 in the pathophysiology of cardiovascular and renal dysfunction, with IL-6 being recognized as a major contributor to kidney diseases." (PMID 40141782, 2025). "Accordingly, we found increasing levels of IFN-γ, IL-6, and IL-17, all known to contribute to renal disease pathology in different models." (PMID 40661967, 2025). "The multifunctional cytokines IL-6 and IL-8, which have pro-inflammatory and pro-fibrotic properties, and their receptors are essential for the onset and progression of kidney disease." (PMID 40119098, 2025). "IL-6, a multifunctional cytokine, plays a crucial role in the occurrence and development of various kidney diseases." (PMID 40007559, 2025). "Preclinical findings in animal models suggest a different role between IL-6, its receptor, and its anti-IL-6 receptor in kidney diseases." (PMID 40243751, 2025). "Improved understanding of the interplay between different IL-6 signaling modes in kidney diseases along with accumulation of clinical experience with IL-6 inhibiting drugs in renal patients will define concrete therapeutic avenues." (PMID 39723211, 2024). "In autoimmune kidney diseases, IL-6 helps immune cells evade ferroptosis, promoting excessive activation of immune cells and worsening kidney disease." (PMID 39749325, 2024). "The latest clinical trials are assessing the efficacy of IL-6 inhibitors on inflammatory markers relevant to cardiovascular and renal diseases." (PMID 39749325, 2024). "Taken together, urinary IL-6 levels have shown predictive value in adult and pediatric kidney diseases." (PMID 39723211, 2024). "Consistent with previous findings, we have confirmed upregulation of several inflammatory mediators, including those modulated by NLRP2, namely Il6, Cxcl1 and Cxcl5 at early and late stages of the kidney disease." (PMID 38633264, 2024). "Expression of gp130 appears to be ubiquitous in the kidney since the classic or trans IL-6 signaling modes were readily detected in renal cell cultures or animal models of kidney diseases." (PMID 39723211, 2024). "Both injured kidney tissue and infiltrating immune cells significantly contribute to elevated local and systemic IL-6 levels in kidney disease." (PMID 39723211, 2024). "Despite promising therapeutic potential of IL-6 inhibiting drugs in kidney diseases, the translation to the nephrological field is delayed by the relative scarcity of clinical information from renal patients and the absence of clear guidelines, respectively." (PMID 39723211, 2024). "Pathophysiologic roles of macrophages in acute and chronic kidney damage are well established, whereas the impact of macrophage-derived IL-6 on the development, course, and resolution of kidney disease is less clear." (PMID 39723211, 2024). "IL-6's involvement in renal innate cell injury, repair processes, and a range of renal diseases stemming from immune responses, metabolic factors, ischemia, and toxins has been clearly demonstrated." (PMID 38327930, 2024).
kidney disease (continued). "Renal IL-6 levels are positively related to mesangial proliferation and tubular atrophy in diverse models of renal disease, supporting the role of IL-6 in the progression of renal disease." (PMID 37736511, 2023). "Pro-inflammatory cytokines, such as tumor necrosis factor (TNF-), interleukin-1 (IL-1), and interleukin-6 (IL-6), play a primary role in renal disease." (PMID 37305825, 2023). "C5α is a potent pro-inflammatory mediator that correlates with the severity of various renal diseases and induces the synthesis of IL-6 and TNF-α in rat GMCs through MAPK signaling pathway activation." (PMID 36791156, 2023). "In regard to their potential to identify disease and its progression, patients with kidney diseases have higher levels of urinary adiponectin, lipocalin-2, leptin, galectin-3 and IL-6." (PMID 37189804, 2023). "This study aims to test the correlations between ROS, SOD3, IL-2, IL-6, and IL-18 and the first kidney disease-related hospitalization or death events in ESRD patients undergoing regular hemodialysis." (PMID 35740095, 2022). "In this study, we aimed to elucidate the correlation between different potential predictors (ROS, SOD3, hs-CRP, IL-2, IL-6, and IL-18) and first nephropathy-related hospitalization or death in ESRD patients receiving hemodialysis." (PMID 35740095, 2022). "IL-6 and TNF-α have been determined to display high expression in CKD while the abnormal expression of IL-10 is also implicated as a risk factor for kidney disease." (PMID 35496058, 2022). "Chronic inflammation is an essential CV risk factor in patients with kidney disease and is characterized by the enhanced production of CRP and other inflammatory mediators, including IL-6 and IL-8." (PMID 35453489, 2022). "One of the potential mechanisms adding to the relationship between DII and the risk of renal disease is the impact of diet-related chronic inflammation in the upregulation of various pro-inflammatory mediators like TGF-β, TNF-α, IL-6, and CRP." (PMID 36313098, 2022). "Blood samples from all participants were collected for ROS, SOD3, IL-2, IL-6, and IL-18 measurement at the beginning of the study, and every kidney disease-related admission or death was recorded for the next year." (PMID 35740095, 2022). "STAT3 proteins are key downstream TFs induced by IL-6 cytokines involved in the pathogenesis of kidney disease that can be activated by binding to phosphorylated tyrosine residues on the cytoplasmic tails of activated cytokine receptors." (PMID 36246123, 2022). "Concurrent to our study, another study reported that IL-6 has a more active role in renal diseases than IL-1β." (PMID 35743930, 2022). "Interleukin 6 (IL-6) is one of the interleukins secreted by leukocytes and the most studied in kidney disease due to its pro-inflammatory effects." (PMID 35887386, 2022). "The functions of IL-6 in kidney diseases have been well studied, its involvement and pro-inflammatory actions enhance endothelial permeability, resulting in microalbuminuria in early DN." (PMID 34402375, 2021). "IL-6 cytokine family members can play either a deleterious or a protective role in response to kidney disease." (PMID 34205404, 2021). "AKI stimulates release of pro-inflammatory cytokines (TNFα, IL-6), further exacerbating kidney disease." (PMID 34025658, 2021). "TNF-α, an important regulatory factor, which can promote the production of IL-6, IL-1β, and other cytokines, participates in inflammation, oxidative stress and damage in various renal diseases." (PMID 32765640, 2020). "Both IL-6 and TNF-α are pleiotropic cytokines that have been implicated in various forms of renal disease." (PMID 33343804, 2020). "Several mechanisms have been proposed to clarify the role of IL-6 in renal impairment; for instance, IL-6 can promote renal disease by increasing sensitivity of tubular epithelial cells to pro-fibrotic cytokines such as TGF-β." (PMID 32961074, 2020).
kidney disease (continued). "As highlighted in this review, multiple members of the IL-6 cytokine family are involved in a variety of kidney diseases." (PMID 30871285, 2019). "We also explore the possibilities of targeting IL-6 cytokine family signalling as viable therapies for the treatment of a range of kidney diseases, as elevated levels IL-6 cytokine family members is a common feature of these diseases." (PMID 30871285, 2019). "With additional knowledge and more sophisticated therapies, targeting IL-6 cytokine family members will become a viable strategy to treat kidney diseases." (PMID 30871285, 2019). "There are many therapies that target IL-6 cytokine family members to treat kidney diseases currently being investigated in clinical trials at various phases, which include kinase inhibitors and IL-6 neutralising antibodies." (PMID 30871285, 2019). "This review will explore the emerging roles that interleukin 6 (IL-6) cytokine family members play in the pathogenesis of kidney disease." (PMID 30871285, 2019). "Genetic studies have linked IL6 gene polymorphisms with progression of kidney function decline, highlighting the important role of IL-6 in kidney disease." (PMID 31001673, 2019). "Evidence from both preclinical and clinical sources show that IL-6 cytokine family members can play either a deleterious or protective role in response to kidney disease." (PMID 30871285, 2019). "More specifically, decreases were observed in autoantibody titers, renal disease severity, and levels of IFNα and IL-6." (PMID 24252506, 2013). "Available data suggests that IL-6 inhibition may be renoprotective in some kidney disorders, but the setting of kidney aging has received only minor attention." (PMID 41677590, 2026). "Metabolic disorders in individuals with kidney diseases may activate the NF-κB signaling pathway, facilitating the release of inflammatory mediators such as IL-6 and TNF-α." (PMID 41356816, 2025). "Physiologically, the progression of kidney disease leads to the accumulation of uremic toxins and increased inflammatory cytokines, such as interleukin-6 (IL-6), which negatively affect brain function and mood regulation, thereby linking kidney disease to depressive symptoms." (PMID 40297143, 2025). "The existing literature is somewhat conflicting with respect to the role of statins in controlling levels of IL-6, two recent meta-analyses discrediting any role of statins for improvement of the IL-6 concentration in either cardiovascular or renal disease patients." (PMID 40868832, 2025). "A higher level of n-6 PUFA is associated with an increased generation of pro-inflammatory mediators, such as interleukin 6 (IL-6), which may accelerate the deterioration of renal disease." (PMID 40243749, 2025). "Although this association is not yet comprehensible, a tie-up between renal disease and markers of inflammation - interleukin-6 (IL-6), preceded by TNF-α - is eminent." (PMID 38883059, 2024). "IL-6 inhibiting therapy has entered the nephrological care with clinically proven benefits for renal transplant recipients and emerging perspective in a wide range of kidney diseases." (PMID 39723211, 2024). "In addition, anti-IL-6 therapy also effectively improved inflammatory markers and proteinuria levels in patients with kidney disease, leading to a reduction of kidney inflammation." (PMID 39749325, 2024). "Based on these considerations, flexible dosage adjustment of IL-6-neutralizing antibodies may represent a viable approach towards a personalized therapeutic effect in various kidney diseases." (PMID 39723211, 2024). "Therefore, introduction of IL-6 signaling inhibitors into clinical nephrology bears great potential to reduce the morbidity and mortality related to kidney disease." (PMID 39723211, 2024). "IL-6 is considered to be an important contributor to kidney diseases." (PMID 37996879, 2023).